HDAC6 (histone deacetylase 6)
Diseases named in the same sentence as HDAC6 in open-access papers (continued):
Sharing a sentence is not in itself a finding about the gene and the disease.
tumor (continued). "Cytoplasmic HDAC6 has been shown to interact with proteins such as α-tubulin, cortactin, heat shock protein 90, β-catenin, and peroxiredoxins, playing a role in the regulation of apoptosis, tumor growth and migration." (PMID 39958888, 2025). "HDAC6 also can deacetylate β-catenin at lysine 49 and inhibit β-catenin phosphorylation at serine 45, promote epidermal growth factor–induced β-catenin nuclear localization, and lead to tumor cell proliferation." (PMID 39736396, 2025). "Abnormal expression of HDAC6 can lead to oncogenic cell transformation and tumor metastasis." (PMID 40649308, 2025). "Notably, ACY-1215 (ricolinostat), a well-known HDAC6 inhibitor, has shown efficacy inducing cell proliferation inhibition, apoptosis, and G1 cell cycle arrest, exhibiting significant anti-tumor effects in TNBC cells." (PMID 41300448, 2025). "Consequently, immunohistochemistry (IHC) analysis showed HDAC6 and Ki67 levels were significantly elevated, while acetylated α‐tubulin levels were significantly reduced in xenograft tumor tissues overexpressing METTL3." (PMID 39535388, 2025). "Additionally, HDAC6 is highly expressed in M-MDSCs and selective inhibitors decrease their immunosuppressive function in tumor-bearing mice." (PMID 39891718, 2025). "Inhibition of Histone Deacetylase 6 (HDAC6) combined with the immune checkpoint blockade (anti-PD-L1) can treat ARID1A-mutated OCCC by enhancing cytotoxic T cell activity and modulating the tumor immune microenvironment." (PMID 40656893, 2025). "Since specific HDAC family members, such as HDAC6, are overexpressed in different tumor types, the development of selective HDACi has corroborated the idea of a focused targeted therapy, rather than using pan-HDACi that may exert multiple effects." (PMID 41458974, 2025). "Cortactin may be considered a significant predictive marker of tumour progression and reduced survival in prostate cancer, and its regulation by HDAC6 may also contribute to its role in poorer patient outcomes." (PMID 39941046, 2025). "HDACs such as HDAC1, HDAC3, and HDAC6 are frequently overexpressed in solid tumors, promoting malignant phenotypes through the repression of tumor suppressor genes, enhancement of epithelial–mesenchymal transition (EMT), immune evasion, and increased angiogenesis." (PMID 41150792, 2025). "Interestingly, HDAC6 KO mice are viable and fertile indicating that this isozyme is an ideal pharmacological target to modulate tumor and immune functions with a favorable therapeutic index." (PMID 40433358, 2025). "HDAC6 primarily targets cytoplasmic nonhistone proteins, including α-tubulin, heat shock proteins, cortactin, and certain tumor-associated antigens." (PMID 40649308, 2025). "Notably, inhibition of HDAC6 with Tubastatin A markedly slowed tumour growth, lowered IL-1β levels, and shifted the immune landscape toward an anti-tumour profile; reducing M2 macrophages while enhancing M1 macrophage responses." (PMID 41440367, 2025). "HDAC6 inhibitors may be of great significance in tumor immunotherapy and related combination strategies." (PMID 38231305, 2024). "This unveils novel insights into the HDAC6 inhibitor ISOX in anti-tumor responses." (PMID 38229155, 2024). "Interestingly, the elevated expression of HDAC6 in the tumor microenvironment also plays a critical role in sustaining an immunosuppressive state, which supports tumoral growth and progression in ovarian and breast cancer." (PMID 39409979, 2024). "HDAC6 is also known to modulate the tumor immune microenvironment." (PMID 39063958, 2024). "ACY-1215 is a selective inhibitor of HDAC6, which can inhibit the growth of a variety of tumor." (PMID 38231305, 2024). "The convergence of bortezomib, a proteasome-targeting agent, with an HDAC6 inhibitor, specifically directed at aggregates within tumor cells, engenders heightened accumulation of polyubiquitinated proteins, consequently inducing increased cellular stress and death." (PMID 38654286, 2024).
tumor (continued). "HDAC6 controls tumor cell proliferation and apoptosis through its interaction with Hsp90." (PMID 39063958, 2024). "To determine whether the HDAC6 inhibitors that enhanced SIINFEKL presentation also promoted T cell–mediated tumor lysis, we employed the B3Z T-cell hybridoma system." (PMID 38747592, 2024). "Our data are consistent with the results from other research groups, which show that HDAC6 inhibitors could be safely combined with other anti-tumor drugs and reporting the HDAC6 score as a potential predictive biomarker." (PMID 39594707, 2024). "Additionally, for the selection of the best HDAC6 IHC cutoff value, future studies will be necessary to define the percentage of immunopositive tumor cells useful to distinguish patients with different disease behaviors." (PMID 39594707, 2024). "In this paper we described the cytotoxic and antiproliferative potency of LASSBio-2208 on different tumour cell lines, its possible synergism effect in association with PI3K and HDAC-6 inhibitors, and its drug metabolism and pharmacokinetics (DMPK) in vitro profile." (PMID 38543175, 2024). "Furthermore, expression levels of biomarkers revealed higher ATP6V0D1 expression in both metastatic and tumour samples, while HDAC6 expression was higher in normal as well as metastatic samples." (PMID 38632516, 2024). "Furthermore, there was a notable difference in HDAC6 expression between early and advanced stage OSCC samples, suggesting a potential association between HDAC6 levels and tumor aggressiveness." (PMID 38702756, 2024). "These suggest that HDAC6 inhibitors may be of great significance in the study of tumor immunotherapy." (PMID 38231305, 2024). "Inhibiting HDAC6 can restore cilia expression and inhibit tumor growth." (PMID 37666811, 2023). "HDAC6 displays important roles in many biological processes and potentially regulates several cellular functions, including cycle regulation, DNA repair, actin-dependent cell motility, and tumor metastasis, respectively." (PMID 37545520, 2023). "HDAC6 is involved in multiple phases of the epithelial–mesenchymal transition (EMT) by which tumor cells lose epithelial characteristics, cell-to-cell junctions, reorganize their cytoskeleton, increase cell motility, and acquire properties that are typical of mesenchymal cells." (PMID 38258065, 2023). "This is relevant for CRC as this tumor may show increased activation of this signaling pathway as well as increased expression of HDAC6." (PMID 38258065, 2023). "Also, both VIPN and tumor growth were alleviated by the inhibition of histone deacetylase 6 (HDAC6) in mice." (PMID 37046624, 2023). "Despite these challenges, the development of dual HDAC6 inhibitors could be important for further tumor treatment and overcoming the problems of the currently approved therapy with pan-HDAC inhibitors." (PMID 38004560, 2023). "HDAC6 upregulation contributes to lymphoma cell survival, drug resistance, and tumor progression." (PMID 37345170, 2023). "In RMS cells, HDAC6 regulates cytoskeletal dynamics through the Rho family GTPase Rac1 to promote tumor cell migration and invasion, and targeting the HDAC6-Rac1 axis may be a therapeutic target for RMS." (PMID 38148899, 2023). "Knock-down of HDAC1 or HDAC6 in vivo led to a more circumscribed less invasive tumor." (PMID 37528157, 2023). "After 5 d of inoculation, either HDAC6 or GRP78 silencing showed a gradual reduction in the tumor spheroid growth rate, while double knockdown of both HDAC6 and GRP78 exhibited the greatest inhibitory effect, corresponding to an increase in tubulin acetylation and a decline in p-ERK expression." (PMID 36639650, 2023). "Besides, some researchers also found that HDAC6 catalyzes the deacetylation of α-tubulin and increases cell mobility and tumor metastasis." (PMID 39282225, 2023).
tumor (continued). "HDAC6 has been identified as a major driver of ciliary disassembly, so several authors suggested that treatment with HDAC6 inhibitors may lead to increased length and number of PCs, concomitant with a suppression of tumor growth." (PMID 37510333, 2023). "In this review, we summarize the advances in tumor treatment with dual-target HDAC6 inhibitors." (PMID 38004560, 2023). "Due to the evidence that HDAC6 inhibition improves cognitive dysfunction in neurodegenerative models, attenuates neuroinflammation, and enhances tumor control, HDAC6 inhibitors may be an ideal candidate for pharmaceutical intervention of CICD." (PMID 34976203, 2022). "HDAC6 inhibition exerts anti-tumor effects both in vitro and in vivo." (PMID 36076996, 2022). "In addition, it has been reported that HDAC6 can regulate the acetylation of α-tubulin and, thus, participate in tumor development." (PMID 35676659, 2022). "HDAC6 inhibition induces an in vivo delay in tumor growth and downregulates PD‐L1 expression." (PMID 35359455, 2022). "In addition to affecting the biological behavior of the tumor itself, HDAC6 also plays a role in regulating the TME." (PMID 36270986, 2022). "Our small molecule screen assay and subsequent mechanistic studies demonstrated that epigenetic modifiers enhanced the chemotaxis and cytotoxicity of γδ T cells through upregulating MICA/B, inhibiting HDAC6/7 pathway and downregulating the levels of PD‐L1 and PD‐L2 in CAFs and tumour cells." (PMID 35731974, 2022). "This could provide further explanation for the role of HDAC6 in tumorigenesis and tumor survival in breast cancer, pointing to a multi-level regulation of these processes." (PMID 35110592, 2022). "In general, new and more selective HDAC6 inhibitors have been disclosed as useful tools to counteract tumor progression, although it was also reported that the selective inhibition of HDAC6 is not necessarily related to an anticancer activity, as observed for Tubathian A and related compounds." (PMID 35745586, 2022). "Previous research has shown that HDAC6-selective inhibitors delayed tumor initiation and progression in vivo without causing any significant adverse effects." (PMID 35359455, 2022). "Decreased H3K27ac peaks were observed within the HDAC6 locus in LIPG-depleted tumor cells." (PMID 35954428, 2022). "However, recent studies on the effect of HDAC6 inhibitors in tumor-infiltrating Treg cells are seemingly contradictory." (PMID 36581745, 2022). "In addition, HDAC6 inhibitors have been demonstrated to cause the activation and membrane translocation of phosphatase and tensin homologue (PTEN), a well-known tumour suppressor gene inhibiting PI3K/Akt signalling." (PMID 35135529, 2022). "Since HDAC6 can increase the expression of PD-L1, inhibiting HDAC6 might enhance the efficacy of tumor immunotherapy." (PMID 36076996, 2022). "Hence, blocking PD-L1 together with the HDAC6 inhibitor ACY-1215 showed combinatory anti-tumor effects which were dependent on CD8+ T cells." (PMID 33859645, 2021). "Moreover, SET7 inhibited cell proliferation and migration by acting on HDAC6 substrate; furthermore, it is involved in tumor suppression by increasing levels of acetylated α-tubulin mediated by HDAC6." (PMID 34938729, 2021). "HDAC6 inhibitors are known to affect a myriad of cellular functions essential in tumor progression." (PMID 34345016, 2021). "Once we saw that the silencing of HDAC6 by interfering siRNAs decreases cell proliferation and the clonogenic capacity of tumor cell lines, we wondered if this silencing could also decrease cell migration." (PMID 34073238, 2021). "HDAC6 may nonetheless be functioning through primary cilia to maintain the tumor proliferative state." (PMID 33915983, 2021).
tumor (continued). "Once we saw that the three tumor cell lines presented HDAC6 overexpression both at the mRNA and at the protein level, we also wanted to study if they had a well-formed primary cilium since HDAC6 has acetylated α-tubulin as its target, one of the structural proteins of the primary cilium." (PMID 34073238, 2021). "Indeed, to our knowledge, besides HDAC2, the only enzyme controlling acetylation/deacetylation of proteins regulated by nitrosylation in tumor cells is the class IIb HDAC6." (PMID 34947954, 2021). "Interestingly, HDAC6 inhibition inhibited tumor cell proliferation, and when knocked down cells were inoculated in animal models a decreased PD-L1 production and an augmented T-cell-mediated immune response was obtained." (PMID 34575678, 2021). "The overexpression of HDAC6 reported in GBMs could partially explain these tumor characteristics, as higher levels of HDAC6 could promote the disassembly of cilia, hence keeping the frequency of ciliated cells low." (PMID 33915983, 2021). "Furthermore, the partial restoration of ciliary expression in CCA cells by inhibition of either HDAC6 or SIRT1 has been linked to decreased cell growth and migration in the tumor cells." (PMID 35096835, 2021). "Numerous studies have revealed that HDAC6 is required for oncogenic cell transformation and tumour cell movement and invasion, and these studies have indicated that HDAC6 inhibition could improve the efficacy of anticancer treatment." (PMID 33744850, 2021). "Numerous studies have found that HDAC6 could stimulate tumor progression by promoting tumor cell transformation, thereby facilitating tumor proliferation, and regulating tumor immunity." (PMID 32705446, 2021). "HDAC6 has been also reported the two opposite regulation of PD-L1 in different tumor types." (PMID 34880761, 2021). "The use of selective drugs against HDAC6 in combination and/or as adjuvant therapy could therefore represent an effective strategy to enhance tumor cell chemosensitivity by interfering with the autophagic process, thus promoting cell death." (PMID 34944907, 2021). "In addition to KMT2D, the authors identified seven more epigenetic regulators in CM cell lines (KDM1A, APOBEC2, HDAC6, KMT2F, SETD4, KAT4, and KDM5B) whose loss accelerates CM tumor progression." (PMID 34575678, 2021). "The relationship between HDAC6 and cilia formation/disassembly in tumor cells could also be more complex and depend on other factors that localize or activate HDAC6 at the ciliary base." (PMID 33915983, 2021). "Recent studies have identified the role of HDAC6 in tumor development and immune metabolism, but its specific function remains unclear." (PMID 34485153, 2021). "Collectively, these findings suggest that HDAC6 inhibition may promote a tumor microenvironment that is amenable to ICI treatment." (PMID 34552864, 2021). "Furthermore, IHC analysis of 36 paraffin-embedded EC tissues and 8 normal endometrial tissues showed that HDAC6 was expressed mainly in the cytoplasm and that the staining intensity increased with increasing tumour grade." (PMID 32107418, 2020). "While elevated Chk1 activity has previously been reported to contribute to tumoral genomic stability, constitutive Chk1 expression and activation resulting from HDAC6 knockdown appears to serve as a detriment to the ability of irradiated NSCLC tumor cells to withstand ionizing radiation." (PMID 33020410, 2020). "Additionally, we confirmed for the first time in vivo that selective inhibition of HDAC6/10 induces intracellular doxorubicin accumulation in zebrafish tissues and engrafted tumor cells, an effect we had observed previously only in cell culture." (PMID 33121173, 2020). "In our previous study, N-hydroxy-4-(2-methoxy-5-(methyl(2-methylquinazolin-4-yl)amino)phenoxy)butanamide (23BB) as a highly selective HDAC6 inhibitor has been designed, synthesized and substantiated by anti-tumor activity in both solid and hematologic tumor models with good safety." (PMID 31894849, 2020).
tumor (continued). "Recently, a study showed that HDAC6 inhibitors improve anti-PD-1 immune checkpoint blockade therapy by decreasing the anti-inflammatory phenotype of macrophages and down-regulation of immunosuppressive proteins in tumor cells." (PMID 32500025, 2020). "Combined with the previous evidence and the present results, we speculated that miR-601 serves as an oncogene in GC, and might promote tumor cell proliferation, migration, and invasion via regulating the expression of HDAC6." (PMID 31547835, 2019). "Furthermore, HDAC6 plays an important role in misfolded/unfolded protein degradation, in addition to its roles in cell morphology, adhesion, migration, and tumor cell invasion/metastasis." (PMID 31024851, 2019). "Notably, non-selective HDAC inhibitors are known to upregulate PD-L1 on the cell surface of tumor cells while selective HDAC6 inhibitor would show the opposite effect by decreasing the expression of PD-L1." (PMID 31652644, 2019). "Further investigations are needed to explore whether WMJ-J-09’s anti-tumor mechanisms involves other HDAC isoforms besides HDAC6 and HDAC8." (PMID 29545751, 2018). "Consequently, high expression of HDAC6 promotes tumor development not only by facilitating cell metastasis but also by preventing misfolded proteins from degradation." (PMID 29593536, 2018). "Together, these findings suggest that HDAC6 is indispensable in tumor immunity." (PMID 30176876, 2018). "Moreover, HDAC6 inhibitors have been shown to enhance tumor control in Phase I and II clinical trials." (PMID 30270813, 2018). "Consequently, a selective HDAC6 inhibitor (ACY-241) enhanced pomalidomide anti-tumor response in MM and ricolinostat (ACY-1215) is in test in combination with BTZ and dexamethasone for relapsed or refractory MM." (PMID 29707147, 2018). "In addition, inhibition of the HDAC6 activity can suppress tumourigenesis and diminish tumor cell migration." (PMID 29391412, 2018). "Thus while tubacin and tubastatin A inhibit HDAC6 with similar selectivity and potency, our results reveal unique HDAC6-independent activities of tubacin that likely contribute to its potent anti-tumor activity." (PMID 29423038, 2018). "We therefore hypothesized that SPOP exerts its tumor suppressor function partly through regulating the stability of HDAC6 oncoprotein." (PMID 28599312, 2017). "HDAC6 has been shown to promote tumour formation in mouse models." (PMID 28668087, 2017). "Additionally, the results of immunohistochemistry showed that TDP-43 and HDAC6 collaborated in GBM-tumor lesions and negatively correlated with the relapse-free survival of GBM patients." (PMID 28915616, 2017). "This study uncovers a novel function for the CTLH complex and suggests that it could have a tumour suppressive role in restricting HDAC6 oncogenic properties." (PMID 28668087, 2017). "Our previous study showed that overexpression of HDAC6 could promote tumor cell growth by activating oncogene c-myc." (PMID 26848526, 2016). "Interestingly, all 3 tumor tissues with activated K-ras mutants showed increased level of HDAC6, suggesting a positive role of K-ras on HDAC6 expression." (PMID 26848526, 2016). "We investigated mechanisms responsible for survival of tumor cells treated with a HDAC6 inhibitor." (PMID 27362804, 2016). "This work suggests that HDAC6 may be an attractive therapeutic target against tumor progression and metastasis." (PMID 27499032, 2016). "Importantly, small molecule inhibitors for HDAC6 already exist and are in clinical trials for other tumor types." (PMID 26643555, 2015). "We further analyzed the frequency of cytoplasmic and nuclear HDAC6 expression in the tumor samples." (PMID 26388610, 2015).